RCBTB1 (RCC1 and BTB domain containing protein 1)
Description:
May be involved in cell cycle regulation by chromatin remodeling.
Synonyms: CLLD7; FLJ10716; CLLL7; GLP; RDEOA
Tractability: PROTAC: ubiquitination databases record sites on it.
Gene: Protein-coding gene on chromosome 13 (49,531,944 to 49,586,740, reverse strand). Ensembl gene ENSG00000136144.
Subcellular location: Nucleus
Subcellular location (Human Protein Atlas): Nucleoplasm
Gene Ontology:
Molecular function: protein binding
Cellular component: cytoplasm; nucleus
Genetic constraint (gnomAD): Loss-of-function variants: 29 observed, 52.67 expected, observed/expected ratio (o/e) 0.55, 90% interval 0.41 to 0.75. The upper end of that interval is the gene's LOEUF score, 0.75, which puts it in group 3 of 6, group 1 being the genes least tolerant of losing a copy. Missense variants: 477 observed, 581.82 expected, observed/expected ratio (o/e) 0.82, 90% interval 0.76 to 0.88. Synonymous variants: 194 observed, 217.79 expected, observed/expected ratio (o/e) 0.89, 90% interval 0.79 to 1.
Gene-disease validity (ClinGen):
ClinGen rates the evidence that RCBTB1 causes each of these diseases.
RCBTB1-related retinopathy (autosomal recessive): Definitive.
Homologues: Orthologues: chimpanzee RCBTB1 (100% identical), macaque RCBTB1 (99% identical), dog RCBTB1 (99% identical), pig RCBTB1 (98% identical), rabbit RCBTB1 (98% identical), guinea pig RCBTB1 (97% identical), mouse Rcbtb1 (96% identical), rat Rcbtb1 (96% identical), zebrafish rcbtb1 (82% identical), tropical clawed frog rcbtb1 (74% identical), Drosophila melanogaster ca (22% identical), Caenorhabditis elegans ran-3 (15% identical), and 2 more. Paralogues in human: RCBTB2 (70% identical), RPGR (25% identical), HERC1 (22% identical), SERGEF (21% identical), RCC1L (20% identical), ALS2 (19% identical), RCC2 (18% identical), RCC1 (15% identical), RCCD1 (9% identical).
Diseases named in the same sentence as RCBTB1 in open-access papers:
RCBTB1 is named in the same sentence as 21 diseases in open-access papers, as found by Europe PMC text mining. Sharing a sentence is not in itself a finding about the gene and the disease. The quoted sentences say what the papers report.
lymphocytic leukemia (2 papers, 2021 to 2024). "Chronic lymphocytic leukemia deletion gene 7(CLLD7) orRCC1 and BTB domain-containing protein 1(RCBTB1) andchromosome condensation 1-like(CHC1L) orRCC1 and BTB domain-containing protein 2(RCBTB2) are potential tumor suppressor genes located at 13q14.3 telomeric toRB1." (PMID 37311552, 2024). "Chronic lymphocytic leukemia deletion gene 7 (RCBTB1, also called Clld7) has been described as a general candidate tumor suppressor." (PMID 34696794, 2021).
retinal disease (2 papers, 2021 to 2023). "Mutations in the RCBTB1 gene cause inherited retinal disease; however, the pathogenic mechanisms associated with RCBTB1 deficiency remain poorly understood." (PMID 37408192, 2023). "Mutations in the RCC1 and BTB domain-containing protein 1 (RCBTB1) gene have been reported to cause a spectrum of inherited retinal diseases (IRDs)." (PMID 37408192, 2023).
leiomyosarcoma (1 paper, 2019). An uncommon, aggressive malignant smooth muscle neoplasm, usually occurring in post-menopausal women. "In vitro and in vivo, RCBTB1 overexpression in leiomyosarcoma cells specifically sensitized to docetaxel-induced apoptosis." (PMID 30641971, 2019).
lipoma (1 paper, 2024). A benign, usually painless, well-circumscribed lipomatous tumor composed of adipose tissue. "Therefore, genes known to be related to lipomas were also considered as potential candidate genes, and included SPRYD7, LHFPL6, RCBTB2, RCBTB1, and CDK4." (PMID 39719593, 2024).
liposarcoma (1 paper, 2019). A usually painless malignant tumor that arises from adipose tissue. "Reciprocally, RCBTB1 downregulation dramatically decreased proliferation of dedifferentiated liposarcoma cells." (PMID 30641971, 2019). "Data reported here evidenced that RCBTB1 expression impacts docetaxel-induced apoptosis in dedifferentiated liposarcoma (LPS80) and LMS (IB112, IB136) cell lines." (PMID 30641971, 2019). "In addition, the most frequently deleted histotype is in LMSs, with 58% RCBTB1 deletion against 36% in the rest of the cohort #1 (UPSs, myxofibrosarcomas, pleomorphic liposarcomas, dedifferentiated liposarcomas, and other sarcomas combined) (Chi-squared test; p = 3.64e-2)." (PMID 30641971, 2019).
melanoma (1 paper, 2021). A malignant, usually aggressive tumor composed of atypical, neoplastic melanocytes. "The antagonistic pathogenesis of vitiligo in relation to cancer specific enhanced cell motility and/or metastasis on typical melanoma predilection sites underlines a plausible involvement of RCBTB1, LITAFD, NUBPL, and PTP4A1." (PMID 34696794, 2021).
metastatic tumors (1 paper, 2019). "Moreover, low RCBTB1 expression is significantly associated with metastatic disease (Chi-squared test; p = 0.046)." (PMID 30641971, 2019). "RCBTB1 is the most frequently deleted gene significantly associated with metastatic evolution (Chi-squared test p = 6.44e-3, lost in 63% of metastatic tumors against 34% of non-metastatic tumors." (PMID 30641971, 2019). "This brought out a gene belonging to the “cell cycle” biological pathway, RCBTB1 (RCC1 And BTB Domain Containing Protein 1), which is lost and downregulated in 62.5% of metastatic tumors against 34% of non-metastatic tumors." (PMID 30641971, 2019).
osteosarcoma (1 paper, 2021). A usually aggressive malignant bone-forming mesenchymal neoplasm, predominantly affecting adolescents and young adults. "Zhou and Münger investigated biological functions of RCBTB1 in osteosarcoma cell lines and found that this protein is responsible for inhibited cell growth and decreased cell viability." (PMID 34696794, 2021).
ovarian carcinoma (1 paper, 2016). A malignant neoplasm originating from the surface ovarian epithelium. "Of the 19 predicted miR-21-3p target genes analyzed, only three genes (RBPMS, RCBTB1 and ZNF608) were confirmed as miR-21-3p target genes in ovarian cancer cells." (PMID 27166999, 2016). "A2780 ovarian cancer cells expressed lower levels of miR-21-3p and higher levels of RBPMS, RCBTB1, and ZNF608 as compared to A2780CP20 cells." (PMID 27166999, 2016). "In addition, we identified RBPMS, RCBTB1 and ZNF608 as targets of miR-21-3p in cisplatin-resistant ovarian cancer cells." (PMID 27166999, 2016).
Retinal dystrophy (1 paper, 2021). Retinal dystrophy is an abnormality of the retina associated with a hereditary process. "Biallelic mutations in the RCBTB1 gene cause retinal dystrophy." (PMID 34617687, 2021).
sarcoma (1 paper, 2019). A usually aggressive malignant neoplasm of the soft tissue or bone. "In conclusion, this study shows that RCBTB1 is commonly deleted in sarcomas with complex genetics and is associated with metastatic progression." (PMID 30641971, 2019). "RCBTB1 downregulation is associated with metastatic evolution in sarcomas with complex genetics." (PMID 30641971, 2019). "A retrospective study of three sarcoma cohorts revealed that low RCBTB1 expression is prognostic for metastatic progression, specifically in patients that received chemotherapy." (PMID 30641971, 2019). "Given that RCBTB1 has been reported to be involved in drug resistance, we investigated a potential impact of RCBTB1 expression level on the chemosensitivity of sarcomas with complex genomics." (PMID 30641971, 2019). "By selecting altered genes belonging to biological pathways dysregulated in all sarcomas, we identified RCBTB1 (RCC1 And BTB Domain Containing Protein 1), for which downregulation is associated with metastatic progression." (PMID 30641971, 2019). "Among the 261 patients, we selected only sarcoma samples for which we had all of the information about RCBTB1 genomic status and mRNA expression, histotype, and metastatic status." (PMID 30641971, 2019). "By contrast, RCBTB1 inhibition decreased cell proliferation and protected sarcoma cells from apoptosis induced by docetaxel." (PMID 30641971, 2019). "One can hypothesize that GD and G will be equivalent in sarcomas harboring RCBTB1 deletion whereas GD will be more effective than G on sarcomas with preserved RCBTB1 expression." (PMID 30641971, 2019). "Collectively, these data evidenced that RCBTB1 is frequently deleted in sarcomas with complex genomics and that its downregulation is associated with a higher risk of developing metastasis for patients receiving chemotherapy, likely due to their higher resistance to docetaxel." (PMID 30641971, 2019). "In light of this unexpected effect of RCBTB1 on tumor growth and considering that docetaxel specifically inhibits microtubule depolymerization during mitosis, we next investigated whether RCBTB1 expression level modulates mitotic rate in sarcoma cells." (PMID 30641971, 2019). "Furthermore, its pro-proliferative action in our sarcoma cell lines provides at least one explanation for the efficacy of docetaxel, which targets mitotic cells, depending on the RCBTB1 expression level." (PMID 30641971, 2019). "This assumption was also encouraged by the fact that RCBTB1 is located in the 13q14 region, which comprises RB1, a well-known tumor suppressor and among the most frequently altered gene in those sarcomas." (PMID 30641971, 2019). "This does not challenge the major and indisputable role of RB1 in pleomorphic sarcoma oncogenesis, but rather suggests that, in our cohort, the prognostic value of RCBTB1 is independent of RB1 status." (PMID 30641971, 2019). "The fact that RCBTB1 and RB1 have antagonistic roles in cell growth and are frequently co-deleted, as in 50% of our 106 sarcomas, suggests that RCBTB1 may not be just a passenger gene affected by RB1 deletion." (PMID 30641971, 2019). "Nevertheless, although we did not observe in vitro any sensitization effect on IB112 cells after gemcitabine or doxorubicin treatment in our experimental conditions, it is not excluded that high RCBTB1 expression could sensitize other sarcoma models to other chemotherapies than docetaxel." (PMID 30641971, 2019).
schizophrenia (1 paper, 2012). A major psychotic disorder characterized by abnormalities in the perception or expression of reality. "Five were not located in any gene, and four were located in genes (ATP8A2, LHFP, PHF11, RCBTB1, and PIBF1 (C13orf24)) not yet shown to be associated with schizophrenia." (PMID 22214315, 2012).
vitiligo (1 paper, 2021). Generalized well circumscribed patches of leukoderma that are generally distributed over symmetric body locations and is due to autoimmune destruction of melanocytes. "In total, we propose the genes NUBPL, PHF11, SETDB2, RCBTB1, PTP4A1, and at a weaker replication level the genes LITAFD, CARHSP1 and OR2C1 as possible candidates for vitiligo-like depigmentation in grey horses." (PMID 34696794, 2021).
Vitreoretinopathy (1 paper, 2022). Ocular abnormality characterized by premature degeneration of the vitreous and the retina that may be associated with increased risk of retinal detachment. "No other known mutations in FEVR‐related genes have been detected, and the putative genetic cause of vitreoretinopathy phenotype is caused by the RCBTB1 gene." (PMID 35876299, 2022). "A reasonable explanation is that the RCBTB1 gene may cause the RP phenotype in the recessive mode, and the phenotype of vitreoretinopathy in dominant mode, sometimes as a syndrome or asymptomatic phenotype." (PMID 35876299, 2022).
cancer (4 papers, 2013 to 2025). A tumor composed of atypical neoplastic, often pleomorphic cells that invade other tissues. "RCBTB1 deletion could possibly take part in the “Go or Grow” mechanism, which triggers a switch from a proliferative to an invasive phenotype in response to environmental stresses such as hypoxia, as demonstrated in other cancers." (PMID 30641971, 2019).
tumor (4 papers, 2019 to 2025). "RCBTB1 expression loss or downregulation may represent a selective advantage for tumor cells during systemic treatments." (PMID 30641971, 2019). "The highlighted genes PHF11, SETDB2, CARHSP1 and LITAFD, are associated with the innate immune system, while the genes RCBTB1, LITAFD, NUBPL, PTP4A1, play a role in tumor suppression and metastasis." (PMID 34696794, 2021). "Altogether, these results indicate that the sensitization effect of RCBTB1 expression on docetaxel-induced apoptosis is at least due to a higher proportion of mitotic cells, which results in greater tumor growth in vivo as observed with IB136 cell line." (PMID 30641971, 2019). "Understanding these mechanisms will probably shed light on a central role for RCBTB1 deletion in tumor development, as suggested by our bioinformatic analysis and our in vivo experiments." (PMID 30641971, 2019). "Wound-healing assays did not evidence any significant impact of RCBTB1 overexpression on cell migration, thereby suggesting that the prognostic value of RCBTB1 mainly relies on its effect on tumor response to treatment." (PMID 30641971, 2019). "Altogether, these observations led us to formulate the hypothesis that RCBTB1 may be a tumor suppressor gene whose activity could be related to drug response." (PMID 30641971, 2019). "Next, we tested whether RCBTB1 may be a prognostic factor for tumor progression." (PMID 30641971, 2019). "Unexpectedly, we also observed that higher expression of RCBTB1 increases the proportion of mitotic LMS cells in vitro and promotes tumor growth in vivo." (PMID 30641971, 2019). "Indeed, we notice here that RCBTB1 rather acts as an oncogene at cellular level by promoting tumor growth but might physiologically favor a less invasive phenotype, thus clinically appearing as tumor suppressor gene." (PMID 30641971, 2019).
retinopathy (3 papers, 2021 to 2023). "Collectively, clinical observations in RCBTB1-associated retinopathy suggest that the primary lesion is most likely located within the RPE layer, followed by secondary photoreceptor cell apoptosis." (PMID 37408192, 2023). "To study the effects of RCBTB1 deficiency in human RPE cells, we previously generated induced pluripotent stem cell (iPSC) lines from a patient with RCBTB1-associated retinopathy caused by biallelic frameshifting mutations in the RCBTB1 gene." (PMID 37408192, 2023). "Our results help to explain the similarity in disease phenotype between RCBTB1-associated retinopathy and the most severe form of mitochondrial retinopathy." (PMID 37408192, 2023). "In summary, our study provides new insights into the biological role of RCBTB1 in oxidative stress responses and highlights RPE mitochondria as a key target site in the pathogenesis of RCBTB1-associated retinopathy." (PMID 37408192, 2023). "RPE generated from these iPSC lines displayed reduced expression of genes involved in the NFE2L2 oxidative stress pathway, supporting similar findings reported in lymphocytes isolated from patients with RCBTB1-associated retinopathy." (PMID 37408192, 2023). "Here, we investigated the effect of RCBTB1 deficiency on mitochondria and oxidative stress responses in induced pluripotent stem cell (iPSC)-derived retinal pigment epithelial (RPE) cells from control subjects and a patient with RCBTB1-associated retinopathy." (PMID 37408192, 2023). "Of the RCC1 proteins, the first has no obvious orthologs in higher eukaryotes, but the second shares domain architecture with human RCBTB1, a protein mutated in a rare form of retinopathy for which an effect on Ran was postulated." (PMID 34565293, 2022). "Our study provides the first report examining the phenotype of RPE cells derived from a patient with RCBTB1‐associated retinopathy." (PMID 34617687, 2021). "Considering the currently restricted knowledge of RCBTB1‐associated retinopathy, additional studies are required to elucidate the pathogenic mechanisms of RCBTB1 deficiency." (PMID 34617687, 2021). "Here, we characterized the effects of RCBTB1 gene deficiency in retinal pigment epithelial (RPE) cells derived from a patient with RCBTB1‐associated retinopathy and restored RCBTB1 expression in these cells using adeno‐associated viral (AAV) vectors." (PMID 34617687, 2021). "Reduced RCBTB1 expression in patient‐derived iPSC‐RPE was accompanied by reduced expression of oxidative stress response genes activated by NFE2L2, supporting previous observations made in PBMCs derived from patients with RCBTB1‐associated retinopathy." (PMID 34617687, 2021). "The similarity in pathogenesis between these conditions suggests that therapeutic approaches aimed at alleviating mitochondrial dysfunction may be useful for treating RCBTB1-associated retinopathy." (PMID 37408192, 2023). "Recent recognition of the phenotypic similarity between RCBTB1-associated retinopathy and the most severe forms of mitochondrial retinopathy further suggests RPE mitochondria may play a role in disease pathogenesis." (PMID 37408192, 2023). "Given the limited numbers of published studies on RCBTB1‐associated retinopathy, additional clinical cases and laboratory investigations of RCBTB1‐related ocular disease are essential for reconciling the inconsistent phenotypes and disease mechanisms reported previously." (PMID 34617687, 2021). "It remains unclear whether the mitochondrial dysfunction observed is a consequence or a cause of the increased ROS levels in RCBTB1-deficient RPE cells; however, this data indicates that damage to RPE mitochondria is a key pathogenic process in RCBTB1-associated retinopathy." (PMID 37408192, 2023).
RCBTB1 also shares sentences with these, for which no sentence is quoted: retinitis pigmentosa (3 papers); Familial exudative vitreoretinopathy (1); myxofibrosarcoma (1); Oral Squamous Cell Carcinoma (1).